AR (androgen receptor)
Diseases named in the same sentence as AR in open-access papers (continued):
Sharing a sentence is not in itself a finding about the gene and the disease.
prostate carcinoma (continued). "However, when LNCaP cells were grown in charcoal-stripped media for several passages (LNCaP-95), there was an increase in the FUT8 expression indicating androgen ablation as a requisite for the FUT8 overexpression in the AR-positive prostate cancer cells." (PMID 29339807, 2018). "The ability of CARNs to retain progenitor properties even in the absence of AR raises the possibility that CARNs represent a cell of origin for prostate cancers that are particularly susceptible to develop castration-resistance." (PMID 29334357, 2018). "Methylation silencing of TGFBR2 was found in rat prostate cancers, further studies also proved AR/miRNA-21 or AR/miR-2909 positive feedback loop down-regulated the expression of TGFBR2, leading to attenuation of TGF-β mediated Smad2/3 activation and subsequent tumor-suppressive activity." (PMID 29699590, 2018). "Thus, common treatment options for prostate cancer include orchiectomy and hormonal therapy, both of which function by restricting the androgen/androgen receptor interaction." (PMID 30154312, 2018). "This value represents the intracellular equivalent of an apparent binding affinity as measured by inhibitory constant, Ki, and is determined using a cellular target engagement CETSA HT assay following compound incubation with prostate-cancer derived cells endogenously expressing AR." (PMID 29317749, 2018). "In contrast, we found that overexpression of miR-152-3p significantly increased proliferation and migration in LNCaP prostate cancer cells which suggests that regulation by the androgen receptor (AR) may account for the observed differences." (PMID 29703916, 2018). "Based on these limited indirect studies, it suggests that besides AR, other nuclear receptors or transcription factors could also regulate the T:E fusion gene in prostate cancer." (PMID 30042415, 2018). "Because it is commonly accepted that AT2R and AT1R work in a contradictory manner, we hypothesized that AT2R agonism suppresses the proliferation activity in prostate cancer cells and down-regulates AR, similar to ARBs." (PMID 29568400, 2018). "We next sought to determine whether the TLX-induced downregulation of AR expression in prostate cancer cells could be mediated by its direct transrepression of AR gene expression or indirectly via other TLX-controlled downstream signaling pathways." (PMID 29555975, 2018). "Given that AKT signaling and AR are two critical pathways in driving the pathogenesis of prostate cancer, the synergetic inhibition of these two pathways might pose a huge threat on the progression of prostate cancer." (PMID 29523594, 2018). "To examine whether MYLIP interacts with AR in prostate cancer cells, we first performed immunoprecipitation assay using LNCaP cells transfected with flag-tagged MYLIP." (PMID 29707137, 2018). "However, the significance of downregulation of AR in advanced prostate cancer and CRPC progression is still poorly understood and neglected." (PMID 29555975, 2018). "Wu (2013) and coworkers proposed that, due to their steroid-based structure, F could interact with the androgen receptor (AR) and modulate the expression of target genes such as the prostate-specific antigen in prostate cancer cell lines." (PMID 29543748, 2018). "The transcriptional response of the prostate cancer to this high LET damage may have a direct impact on the AR signaling axis and upregulate receptor expression." (PMID 29691406, 2018). "In conclusion, our study provides preliminary evidence that the GI microbiota may be different in men undergoing treatment with androgen receptor axis-targeted therapies commonly used to treat prostate cancer." (PMID 29988102, 2018). "Similarly, pharmacological inhibition of PRMT5 decreased symmetric methylation of H4R3, expression of AR in AR-positive prostate cancer cells, and reduced cancer cell growth." (PMID 30613353, 2018).
prostate carcinoma (continued). "In contrast, TRIM28 high-tumor cells may be favorably selected as TRIM28 overexpression enhances AR signaling, which is a key mechanism to prostate cancer resistance to androgen deprivation therapy." (PMID 30479348, 2018). "However, the expression of AR is highly heterogeneous in prostate cancer specimens, reflecting the heterogeneity of the disease." (PMID 29555975, 2018). "However, the regulation of AR activity in prostate cancer cells by melatonin is likely to be dependent of a rise in intracellular cGMP, leading to an increase in calcium and activation of PKC." (PMID 30386380, 2018). "In the light of these observations, GSK-J4 and DZNeP may be involved in key pathways, PTEN and AR, involved in prostate cancer." (PMID 29805743, 2018). "Thus, Prx II is a therapeutic target for AR-expressing prostate cancers to inhibit its progression to CRPC and to suppress stemness-related characteristics." (PMID 30177619, 2018). "Some recent reports suggest that taxanes can inhibit AR signaling in prostate cancer cells." (PMID 30453546, 2018). "Prostate cancer often develops resistance to androgen receptor (AR) targeting drugs." (PMID 30478344, 2018). "Finally, it has been shown that treating prostate cancer xenografts with inhibitors to AR (bicalutimide) and PARP-1 (Olaparib) inhibits tumor growth." (PMID 30305041, 2018). "Notably, AR and multiple transcription factors extensively reported to be involved in prostate cancer aggressiveness, such as ETV5 and ETV1 were identified as Key TFs with increased transcriptional targets, supporting the biological relevance of our analysis." (PMID 30314329, 2018). "Results have consistently confirmed a critical role for AR activity in prostate cancer progression." (PMID 31328183, 2018). "In addition to the major role of the androgen/AR system in prostate cancer, various GPCRs are involved in the development and progression of prostate cancer." (PMID 30319552, 2018). "This, in turn, stabilized the androgen receptor functions in prostate cancer cells." (PMID 29747682, 2018). "In prostate cancer cells, a melatonin-mediated nuclear exclusion of the androgen receptor has been described, indicating that melatonin might regulate the androgen receptor activity." (PMID 30386380, 2018). "Together, our results suggest that overexpression of TLX could promote androgen-deprivation- and anti-androgen-insensitive growth capacity in AR-positive prostate cancer cells." (PMID 29555975, 2018). "Small-cell prostate carcinoma (SCPC) is a common lethal variant of prostate cancer (PCa) that is androgen receptor (AR) negative and thus represents a mechanism for escape from the potent antiandrogen treatments." (PMID 29600194, 2018). "22Rv1 is a castration-resistant human prostate carcinoma epithelial cell line that is derived from an androgen-dependent CWR22 xenograft that relapsed during androgen ablation; this cell line also expresses the androgen receptor splice variant AR-V7." (PMID 30296942, 2018). "In this study, we propose a new mechanism to inhibit AR expression in prostate cancer cells." (PMID 29988966, 2018). "A remaining problem, however, is that prostate cancer also evolves into an AR-independent cancer after long-term treatment with AR antagonists, and AR antagonist-resistant cells may show elevated metastatic growth." (PMID 30158439, 2018). "It has been hypothesized that the sclerotic phenotype of prostate cancer may originate from intra-tumoral steroidogenesis in castration-resistant prostate cancer and thus preserved androgen levels and AR activity." (PMID 29670000, 2018).
prostate carcinoma (continued). "To test if PTC209 could effectively inhibit the growth of AR-positive prostate cancer and CRPC, we first examined the effect of PTC209 on cell proliferation in AR-positive PCa cell lines LNCaP, VCaP, C4-2, and 22Rv1, and observed a low IC50 (around 0.6 μM)." (PMID 29402932, 2018). "Since both BMI1 and AR are abundantly expressed in prostate cancer cells, whether BMI1 modulates AR protein expression and transcriptional activity remains unclear." (PMID 29402932, 2018). "However, our studies are the first to link the V-ATPase-HIF-1α axis specifically to AR levels in prostate cancer." (PMID 29988966, 2018). "These tumors often exhibit active FGF receptor and MAPK signaling to bypass the AR pathway for sustained prostate cancer growth, and initial preclinical experiments with selective inhibitors show in vitro and in vivo efficacy in double-negative prostate cancer models." (PMID 29734647, 2018). "Relapse in the absence of androgens (castrate-resistant prostate cancer) is inevitable for most individuals and is associated with increased expression and activation of the androgen receptor, a major determinant in survival." (PMID 29914450, 2018). "Similarly, prognostic significance of the GR expression in castration-resistant prostate cancer appears to be dependent on the status of the AR." (PMID 30518063, 2018). "Next, we asked whether CNPY2 could regulate the expression level of AR target genes in prostate cancer." (PMID 29707137, 2018). "Among them, we found that gene CDK5 has isoform switching between prostate cancer and benign tissues, which may affect cancer development by changing androgen receptor (AR) phosphorylation." (PMID 30367578, 2018). "For example, an AR/p52 complex has been shown to be important for prostate cancer growth, an AR/c-Rel complex whose functional role is still unknown." (PMID 30158439, 2018). "Thus, our data suggest that inhibition of HDAC3 effectively suppresses the growth of SPOP‐mutated prostate cancer cells by shutting down both AKT and AR signaling pathways." (PMID 29523594, 2018). "The AR works paradoxically between breast cancer cells and in prostate cancer cells." (PMID 30577860, 2018). "It suggested that in response to ADT in hypoxia, these genes can be restored and increased, and some of which may in turn confer androgen/AR-independent prostate cancer and thus therapy resistance." (PMID 30478344, 2018). "AR protein localization in prostate cancer has been found to influence prognosis." (PMID 30416486, 2018). "Of note, it was shown that the use of S1R antagonists prevented nuclear translocation of androgen receptor (AR), induced proteasomal degradation of AR and its splice variant, ARV7 (frequently detected in castrate-resistant prostate cancer), and consequently suppressed their transcriptional activity." (PMID 30042674, 2018). "While another study showed that Jagged1 combined with androgen receptor could increase Akt phosphorylation, in turn, phosphorylated Akt further regulated cyclin B1 in prostate cancer cells." (PMID 29636838, 2018). "The properties and role of prostate cancer (PCa) stem cells is an active field of research where further investigation is needed to assess the cellular expression of Androgen Receptor (AR) by prostate CSCs, and confirm their ability to give rise to the metastatic form of PCa, namely CRPC." (PMID 30211124, 2018). "Androgen receptor (AR) is a key target in the discovery of anti-PCa (Prostate Cancer) drugs." (PMID 29755968, 2018). "Targeting AKT and AR was more profound when combined with castration (ADT) in prostate cancer." (PMID 29572264, 2018). "Moreover, other papers have reported that: (i) the melatonin levels are lower in prostate cancer patients than in normal men; and (ii) the melatonin interacts with the androgen receptor and modulates the cell growth in prostate cancer patients." (PMID 29844288, 2018).
prostate carcinoma (continued). "Proof of concept for this approach lies in the effective therapeutic targeting of ER and AR in breast and prostate cancer, which exploits the lineage-specific functionality of these transcription factors rather than their genetic alteration, to create a therapeutic window." (PMID 30200227, 2018). "Also, it is reported that downregulation of androgen receptor (AR) induces autophagy in prostate cancer cells." (PMID 30200999, 2018). "Finally, we tested the ability of AR-deleted CARNs to serve as a cell of origin for prostate cancer, based on the previous finding that prostate cancer can initiate from CARNs after specific deletion of Pten and androgen-mediated regeneration." (PMID 29334357, 2018). "PSCC is a male-specific malignancy, which may be similar to prostate cancer that correlates with androgen stimulation and AR expression." (PMID 29880898, 2018). "Re-activation of AR is one of the major factors in the emergence of ENZ resistant prostate cancer." (PMID 30470788, 2018). "As AR is essential for the development of prostate cancer, and EGFR is a key factor for definite lung cancer, future research will be indispensable to pay attention to the stratification of patients before the application of Hsp90-Cdc37-client protein targeted therapy." (PMID 29699578, 2018). "Finally we utilised the 22Rv1 prostate cancer cell line to represent a CRPC model with high AR activity and endogenous expression of both the AR full length and V7 forms." (PMID 29760584, 2018). "Moreover, in human prostate tumor tissues, androgen receptor down-regulation further leads to the development of prostate cancer stem-like cells, which requires STAT3 activity." (PMID 29636641, 2018). "Prx II is considered as a key factor which regulates AR signaling in prostate cancers." (PMID 30177619, 2018). "More recently, CRIF1 was seen to be highly expressed, together with STAT3, in the epithelium and stroma of prostate cancer and to compete with the coactivator p160 for the binding to the androgen receptor (AR), which is known to have a pro-tumorigenic role in this neoplasia." (PMID 29914167, 2018). "However, in prostate cancer, let-7 suppresses AR expression and activity, which in turn leads to decreased cell proliferation and tumor growth." (PMID 29423076, 2018). "Whether SINE (selinexor and KPT-8602 which is a new generation SINE) could regulate important AR signaling in prostate cancer through modulation of AR and ARv remains unknown." (PMID 30450161, 2018). "Moreover, AR is involved in a number of severe diseases, such as prostate cancer (PCa), muscle atrophy, and osteoporosis." (PMID 30639122, 2018). "In addition, the authors demonstrated that expression of Smurf1 in prostate cancer cells is regulated through the androgen receptor (AR) signaling, which is critical for prostate cancer growth and survival." (PMID 30116722, 2018). "We used the androgen‐dependent prostate cancer cell lines LNCaP and MyC‐CaP to test whether TF expression is regulated by AR." (PMID 29427323, 2018). "Other proteins such as the androgen receptor (AR), which is required for growth in both androgen-sensitive and androgen-insensitive prostate cancer are cleaved by calpain in the presence of high Ca2+ concentrations due to the release of calpain from the calpain-CaM-calpastatin complex." (PMID 30319995, 2018). "Plexin-B1 activation increases phosphorylation and translocation into the nucleus of the androgen receptor (AR), leading to activation of AR-regulated genes, which could play a role in castration resistance in prostate cancer." (PMID 29971044, 2018). "Testosterone and DHT are important for AR activation and the sustained growth of prostate cancer." (PMID 30241348, 2018). "The AR is strongly expressed in the stroma in early prostate cancer, but may be decreased in areas surrounding cancerous tissue, especially in androgen-independent cancer, and this can be associated with early relapse." (PMID 29721186, 2018).
prostate carcinoma (continued). "The functional significance of the observed heterogeneity of androgen receptor (AR) expression in prostate cancer is unknown." (PMID 30190514, 2018). "Androgen receptor (AR) is critical to the molecular etiology of prostate cancer progression." (PMID 30651935, 2018). "The functional role of glucocorticoid-mediated GR signaling has been more extensively investigated in the growth of hematological malignancies, as well as that of solid endocrine tumors, such as breast and prostate cancers, relating to its interplay with ER and AR, respectively." (PMID 30518063, 2018). "Both AKT‐mTOR and androgen receptor (AR) signaling pathways are aberrantly activated in prostate cancer due to PTEN deletion or SPOP mutation, two genetic lesions occurring in up to 80% of advanced prostate cancer." (PMID 29523594, 2018). "Taken together, these data suggest that chronic-therapy (ADT)-in-hypoxia may select prostate cancer cells capable of displaying androgen/AR-pathway independence and therapy resistance in hypoxia in vitro and in xenograft tumors in vivo." (PMID 30478344, 2018). "To investigate whether there was a correlation between CNPY2 protein expression and AR protein expression in prostate cancer, we examined CNPY2 and AR in primary prostate cancer tissues." (PMID 29707137, 2018). "Having established that AR-V7 driven prostate cancer remains susceptible to targeting of LSD1, at least in the model systems used here, it will be important to dissect the molecular interaction between chemical LSD1 inhibition and an LSD1:AR interaction." (PMID 29760584, 2018). "In prostate cancers, androgen/AR promotes glucose metabolism in normoxia." (PMID 30478344, 2018). "We conclude that TF, NF‐κB and EGR1 expression may be repressed by AR in prostate cancer patients, and that this signaling axis could also be active in human prostate epithelial cells in vivo." (PMID 29427323, 2018). "The androgen receptor (AR) is a critical therapeutic target for treating advanced prostate cancer." (PMID 30463359, 2018). "Androgens and androgen receptor (AR) are essential for growth and survival of prostate cancer." (PMID 29540470, 2018). "Based on this speculation, we measured the cell proliferation of two androgen receptor-positive prostate cancer cells; LNCaP and 22Rv1." (PMID 29164416, 2018). "miRNA changes mediate therapeutic resistance by a wide set of oncogenic interactions including resistance to apoptosis, inhibition of metabolic regulatory genes (namely FOXO1), and notably the upregulation of AR in prostate cancer, providing a direct link to castration resistance." (PMID 29562686, 2018). "Results showed that the effect of PAC treatment on prostate cancer is mainly achieved through reducing the expression of AR and inhibiting the inflammatory microenvironment in vivo, finally inhibiting prostate cancerproliferation and inducing prostate cancer apoptosis." (PMID 28383015, 2017). "The prognostic value of AR has also been reported in prostate cancer." (PMID 28262798, 2017). "AR is a key transcription regulator that is highly expressed in prostate cancer." (PMID 29228644, 2017). "Together, these results indicate AR may enhance prostate cancer growth and survival by suppressing the induction of FABP4 by PPARγ." (PMID 29181019, 2017). "ADT reduces the level of circulating androgens and therefore levels in the prostate cancer cells resulting in AR not being activated, causing cell cycle arrest and apoptosis." (PMID 27902483, 2017). "In the second proof-of-concept, we demonstrated an automatic classification of epithelial cell populations (n = 83,558) and glands (benign vs. cancer) in prostate cancer with simultaneous analysis of androgen receptor (AR) and alpha-methylacyl-CoA (AMACR) expression at cell-level resolution." (PMID 29138507, 2017). "We determined that androgen-mediated depletion of CXCR7 relies on AR in prostate cancer cells." (PMID 28596572, 2017).